ANGPT2 (angiopoietin 2)
Diseases named in the same sentence as ANGPT2 in open-access papers (continued):
Sharing a sentence is not in itself a finding about the gene and the disease.
tumor (continued). "Taken together, these outcomes indicate that PD-L1 blockade treatment normalizes tumor vasculature and inhibits neovascularization by decreasing the expression of Tie2 and ANGPT2 through a JAK1/2-dependent mechanism." (PMID 40370455, 2025). "Of the 12 chemokines compared, IL-6, Angiopoietin-2, IL-8, and CEACAM-1 were significantly higher in the tumor group (IL-6: p = 0.02, Angiopoietin-2: p = 0.007, IL-8: p = 0.003, CEACAM-1: p = 0.001)." (PMID 39652104, 2025). "High levels of ANGPT2 compared to ANGPT1 positively correlate with tumor vascularity, tumor growth, and poorer prognosis." (PMID 39866233, 2025). "In conclusion, this study innovatively illustrates that IFN-γ-mediated inhibition of ANGPT2-Tie2 in ECs inhibits angiogenesis and normalizes tumor vasculature during immunotherapy." (PMID 40370455, 2025). "Monoclonal antibodies targeting ANGPT2 have demonstrated efficacy in preclinical studies by blocking its action, leading to the inhibition of tumor angiogenesis and a reduction in tumor growth and metastasis." (PMID 40061897, 2025). "And oxidative stress also affects cargo in exosomes, The redoxin sensitive signal path PI3K/Akt/eNOS regulate secrete body release Angiopoietin 2 (Ang2), and the Ang2 is an important participant of tumor vascular remodeling." (PMID 40534881, 2025). "In preclinical studies, deletion of the Angpt2 gene results in a transient delay in primary tumor growth." (PMID 40260291, 2025). "Angiopoietin 2 (Angpt2), essential for forming vessels encapsulating tumor clusters (VETCs), facilitates the entry of the entire tumor cluster into the bloodstream in an invasion-independent manner." (PMID 40161350, 2025). "We then compared the tumor growth curves of ANGPT2 KO (ANGPT2‒/‒) and ANGPT2WT PC12 cells in subcutaneous xenograft models in BALB/c nude mice." (PMID 41400463, 2025). "Recent studies have highlighted the pivotal roles of SPP1, ANGPT2, and NCL in regulating the polarization of tumor-associated macrophages (TAMs), offering a new perspective on their potential as targets for cancer therapy." (PMID 38806553, 2024). "Upregulation of ANGPT2 is associated with T-cell exclusion, and blocking it promotes CD8+ T-cell infiltration, resulting in anti-tumor effects." (PMID 38619734, 2024). "After VEGF blockade, expression level of ANGPT1 increased in a narrow therapeutic window during tumor oxygenation, while ANGPT2 induced vascular remodeling and sprouting under hypoxic TME at Bev resistance." (PMID 38619734, 2024). "ANGPT-2 expression is minimal in physiological conditions but is increased in response to VEGF and hypoxia in tumor-associated vessels." (PMID 38213742, 2024). "The expression level of VEGF-A and ANGPT-2 genes were significantly higher in tumor tissues as compared with normal adjacent tissues (P-value < 0.001)." (PMID 38719941, 2024). "In summary, VEGF-A aligned with all the tumor characteristics we evaluated, FAP was associated with tumor grade, size, and MMR status, and angiopoietin-2 was associated with tumor grade and MMR status." (PMID 39511039, 2024). "This function can be further upregulated by exposure to tumor-derived factors such as angiopoietin-2 (ANGPT2)." (PMID 38787372, 2024). "When EC patients were classified based on tumor grade, significant elevation in the levels of angiopoietin-2 (p = 0.015), FAP (p = 0.033), FGF-1 (p = 0.0004), and VEGF-A (p = 0.018) were observed in the more advanced grade 3 tumors compared to grade 1 tumors." (PMID 39511039, 2024). "CTGF has been identified as an enhancer of vascular endothelial growth factor (VEGF) and angiopoietin 2 expression - essential factors for tumor angiogenesis - thus facilitating tumor growth and metastasis." (PMID 38167009, 2024). "We analyzed the significantly upregulated genes in TDECs related to tumor growth factors and selected Angpt2, Lama4, Egr1, Egr3, and Vegfa." (PMID 39440923, 2024).
tumor (continued). "Both expression of ANGPT1 and ANGPT2 were intensely present in vascular endothelial cells especially in larger sized tumor vessels (≥ 15 μm) and some small vessels (< 15 μm)." (PMID 38619734, 2024). "The ANGPT2-Tie2 axis has emerged as a regulator of tumor angiogenesis, due to it exhibiting high expression in human tumor vascular remodeling as well as very low expression in normal tissue." (PMID 38411438, 2024). "Pericytes play a crucial role in tumor neovascularization; consistently, we observed a strong angiogenic signature (such as for ANGPT2, CAV1, PDGFA, THY1, EGFL6, and GMFG) in pericytes." (PMID 37853464, 2023). "In human and mouse PanNET liver metastases, ANGPT2 upregulation coincided with poor T cell infiltration, indicative of an immunosuppressive tumor microenvironment." (PMID 37843277, 2023). "Firstly, endothelial cells showed decreased expression of mouse Angpt2 and Egln1 genes, which typically promote tumor cell metastasis and the dysregulation of vascular stability." (PMID 37660083, 2023). "While earlier tumor xenograft studies demonstrated the antitumor efficacy of ANGPT2 inhibition in mice, we found that the antimetastatic effects of targeting ANGPT2 are abolished under immunodeficient conditions." (PMID 37843277, 2023). "Estrogen depletion induces BM niche cells to produce angiopoietin-2, which destabilizes the niche by interfering with angiopoietin-1/Tie2 signaling and promotes ER+ tumor cell survival via integrin β1." (PMID 37296983, 2023). "For its part, angiopoietin 2, which is predominantly found in hypoxic tumor tissues, regulates the maturation of BC blood vessels by acting in a complementary manner to the VEGF pathway." (PMID 36834641, 2023). "Blockade of ANGPT2 effectively inhibits angiogenesis and vascular abnormalities in several tumor types by activating Tie225–27." (PMID 36828931, 2023). "On the other hand, the vascular Tie2 level was relatively constant in both brain and tumor tissues, and ANGPT2 expression was restricted to a portion of vessels in the GBM center." (PMID 36828931, 2023). "Patients with high ANGPT2 expression had lower tumor immune dysfunction and exclusion scores and were more likely to benefit from immunotherapy, which provides a reference to guide the use of immunosuppressants." (PMID 37480055, 2023). "ITGA5 and VEGFA were coexpressed in clusters 1 and 3, while ANGPT1 and ANGPT2 were minimally expressed in all tumor cells." (PMID 36999964, 2023). "Dysregulation of VEGF/VEGFR2 and ANGPT2/Tie2 signaling leads to vascular abnormalities in various tumor models." (PMID 36828931, 2023). "Of the 11 neoplasm-related genes in these subclusters, the expression of six (ANGPT2, TP73, NOVA1, CDH11, CXCL12, and LAMA1) were significantly repressed in KRT and one (EPHA2) was higher expressed in KRT compared with IMU." (PMID 37654626, 2023). "Based on this expression pattern, it is unlikely that ANGPT2 and Tie2 are related to the normal-to-tumor vascular changes in the GBM invasion region." (PMID 36828931, 2023). "As angiopoietin-2 (ANGPT2) was expressed in only a portion of the central tumor vessels, we developed a ligand-independent tunica interna endothelial cell kinase 2 (Tie2)-activating antibody that can result in Tie2 phosphorylation in vivo." (PMID 36828931, 2023). "Apoptotic tumor cells, marked by cleaved caspase-3, were greater in metastases of mice treated with anti-ANGPT2 than in IgG-treated controls." (PMID 37843277, 2023). "IFN-γ production of tumor-specific CD8 T-cell responses significantly decreased in the presence of ANGPT2." (PMID 35935946, 2022). "Consistently, the expression of ANGPT2 has been reported to be correlated with microvessel density and tumor size and metastatic efficacy, which suggested ANGPT2 an independent prognostic factor in the progression of multiple cancer types." (PMID 35987690, 2022).
tumor (continued). "ANGPT2 regulates vascular remodeling and tumor progression under many pathological conditions through different effects on TIE2 signaling." (PMID 36172371, 2022). "In this study, when we re-stained the tumor specimens with Angpt2 and CD31, we observed that levels of Angpt2 and CD31 expression in excised tumors were significantly decreased in the SAS/CCL4 shRNA cells." (PMID 35884919, 2022). "Meanwhile, bone morphogenetic protein 1 (BMP1) and ANGPT2, which respectively facilitate tumor growth and angiogenesis, were expressed at significantly higher levels in SMC_1." (PMID 35999201, 2022). "In agreement with this, AA treatment of native patient-derived PCa tumour samples ex vivo inhibits ANGPT2 expression." (PMID 35513564, 2022). "ANGPT2 is expressed at the site of vascular remodeling, such as tumor vessels in the leading and infiltrating edges, as well as microvascular hyperplastic regions of GBM." (PMID 36046049, 2022). "In normal intestinal mucosa, the expression of ANGPT2 is lower than that of intestinal adenoma, and there is a positive correlation between the angiogenic factor and tumor cell proliferation activity." (PMID 36172371, 2022). "The obtained data suggest that AA downregulates ANGPT2 expression in a majority of human tumour samples ex vivo." (PMID 35513564, 2022). "Histological analysis and immunohistochemistry for angiopoietin-2 in the tumor and non-tumor tissue of explanted livers were performed." (PMID 36158651, 2022). "The ANGPT2/TIE-2 axis was implicated in angiogenesis and tumor progression due to its role in the permeabilization of the blood vessels and the activation of TIE-2+-expressing monocytes (TEMs)." (PMID 35935946, 2022). "Staining of GC tissue derived from a subcutaneous tumor model in nude mice showed that ANGPT2 expression in DNAse-1-treated mice was significantly lower than in the control group." (PMID 36172371, 2022). "We then stained rat pituitaries from wild‐type (WT) rats and MENX tumor‐bearing rats and confirmed that Angpt1 is downregulated whereas Angpt2 is upregulated in the tumors (Fig EV1)." (PMID 35266635, 2022). "Analysing the xenografted CRPC tumours from mice reveals that mice treated with AA downregulates the expression of the angiogenic promoting factors ANGPT2 and EDN1 in vivo confirming the previous observation." (PMID 35513564, 2022). "Corresponding to results here and elsewhere, DS patients have been found to have elevated levels of ANGPT1 and ANGPT2, which are protective against tumor metastasis, providing insight into the less solid tumors in DS." (PMID 35947952, 2022). "Together with our first report, our results support that TIE-2+ M-MDSC/ANGPT2 signature represents a tumor escape mechanism across human cancers." (PMID 35935946, 2022). "Angiopoietin-2 (ANG2) is a key driver of tumor angiogenesis and metastasis, and it has been identified in primary GC tissues." (PMID 35740619, 2022). "This is likely due to the fact that Angpt2 secreted in the media by the tumor cells activates the receptor located on their plasma membrane, thereby making these cells not responsive to the recombinant protein (Fig EV3)." (PMID 35266635, 2022). "Angiopoietin-2 is a key driver of tumor angiogenesis and has recently emerged as a promising target for antiangiogenic therapy." (PMID 35740619, 2022). "This suggests that endogenous Angpt2 secreted by the tumor cells contributes to the activation of tumor cell‐bound Tie2." (PMID 35266635, 2022). "Increased levels of plasma/serum ANGPT2 have been reported in patients with various solid cancers, where they correlate with advanced tumor stage, recurrence, and presence of metastases." (PMID 35266635, 2022). "ANGPT2 levels are elevated in cancer, increasing angiogenesis, tumor growth, and metastasis formation." (PMID 35203640, 2022).
tumor (continued). "Equally important was the demonstration that angiopoietin-2 is an independent factor of mortality, emphasizing the extremely important role of the biology of the tumor in defining patients’ prognosis after liver transplantation." (PMID 36158651, 2022). "Angiopoietin 2 (ANGPT2) negatively influences tumor immunity by stimulating Tie-2-expressing monocytes/macrophages to secrete IL-10, leading to the expansion of Treg cells and inhibiting effector T-cell activation." (PMID 36013403, 2022). "We found that ANGPT2 is a carcinogenic factor which is closely related to the tumor microenvironment in GC." (PMID 36172371, 2022). "In tumor tissues, ECs secrete high levels of Angpt2, which works as the main Tie2 ligand and together with VEGFA promotes angiogenesis via both autocrine and paracrine mechanisms." (PMID 35266635, 2022). "ANGPT2 was also expressed in the cytoplasm of sparse adenohypophyseal cells in unaffected pituitaries and, more importantly, in tumor cells, where moderate to strong cytoplasmic immunoreactivity was seen in 27/39 cases." (PMID 35266635, 2022). "It should be noted that ANGPT2 not only drives tumour neo-angiogenesis but also plays a crucial role in the induction of inflammation in the tumour microenvironment." (PMID 35513564, 2022). "ANGPT2 is a member of the angiopoietin (Ang) family, which modulates vascular remodeling and tumor growth in many pathologic situations via its differential influence on TIE2 signaling." (PMID 36613779, 2022). "Another way NETs stimulate tumor initiation and progression is by affecting the expression of the ANGPT2 gene in endothelial cells." (PMID 36613779, 2022). "IF of consecutive tissue sections of rat PitNET tissues confirmed the expression of both Angpt2 and Tie2 in tumor cells, as well as in CD31‐positive ECs used as the positive control (Fig EV1)." (PMID 35266635, 2022). "The results showed that 34.5% of the tumor cells counted had at least one positive interaction between Tie2 and Angpt2, with 68.5% of the positive cells showing only one interaction." (PMID 35266635, 2022). "ANGPT2 can induce therapeutic resistance by increasing angiogenesis and immunosuppressive activity in the tumor microenvironment." (PMID 35157610, 2022). "Tie2 gene deletion blunts PitNETs growth in xenograft models, and pharmacological inhibition of Angpt2/Tie2 signaling antagonizes PitNETs in primary cell cultures, tumor xenografts in mice, and in MENX rats." (PMID 35266635, 2022). "Upon separation of primary tumor cells from primary ECs we found that isolated NF‐PitNET cells from both rat and human cultures secrete Angpt2." (PMID 35266635, 2022). "To confirm that Angpt2 acts as agonist of tumor cells‐bound Tie2, we assessed receptor phosphorylation upon stimulation also by WB." (PMID 35266635, 2022). "Tumor cells hijacking blood vessels can induce expression of angiopoietin 2 and VEGF in vascular endothelial cells, which subsequently results in regression of the blood vessels." (PMID 35951441, 2022). "Elevated plasma ANGPT2 concentration is therefore a putative indicator of more aggressive tumor behavior in PitNETs." (PMID 35266635, 2022). "The results showed that, in contrast to dasatinib, the addition of both regorafenib and rebastinib effectively restored the IFN-γ production by tumor-specific T cells inactivated by ANGPT2 exposition." (PMID 35935946, 2022). "Although NF‐PitNET cells express much higher levels of Angpt2 than Angpt1, ECs secrete Angpt1, which can also promote tumor‐bound Tie2 activation." (PMID 35266635, 2022). "Taken together, these data suggest that androgens promote neo-angiogenesis in CRPC tumours through secretion of ANGPT2 and that AA counter-regulates this process." (PMID 35513564, 2022). "ANGPT2 stimulation of TIE2 in tumor cells activates downstream cell proliferation signals, as previously demonstrated in endothelial cells (ECs)." (PMID 35266635, 2022).
tumor (continued). "Tie2 receptors on tumor cells can bind Angpt2 and this initiates stimulatory autocrine signaling involving the same downstream effectors seen in ECs (e.g., Fak, ERK1/2)." (PMID 35266635, 2022). "We show that PitNET cells express a functional TIE2 receptor and secrete bioactive ANGPT2, which promotes, besides angiogenesis, tumor cell growth in an autocrine and paracrine fashion." (PMID 35266635, 2022). "shAngpt2‐GH3 cells induced less vessel sprouting than control cells (−30%, P = 0.0319), thereby demonstrating that Angpt2 secreted by tumor cells retains the pro‐angiogenic properties of EC‐secreted Angpt2." (PMID 35266635, 2022). "In our study, we found that NETs act on HUVECs to trigger the release of various tumor-related factors, such as ANGPT2, ECM, CD40, and IL-8." (PMID 36172371, 2022). "This transition leads to the activation of many cytokines by matrix metalloproteinases or other proteinases, such as IL-8, VEGF, and angiopoietin 2 (ANGPT2), which promote tumor neovascularization." (PMID 36506099, 2022). "The tumor and intraglandular stromal cells in glandular PCa expresses both angiopoietin-1 and angiopoietin-2." (PMID 33841508, 2021). "Among the 47 matched specimens, ANGPT2 was seen in all GC tissue and increased compared to adjacent non-tumor tissue." (PMID 33758610, 2021). "Expression of angiopoietin-2 by tumor cells induces the recruitment of Tie2-expressing monocytes in the tumor." (PMID 35011579, 2021). "In order to elucidate the role of the signature genes’ biological functions, the association of STMN1, RAP1A, FLT3, HSPA8, ANGPT2, and PGF was positively associated with tumor purity in HCC." (PMID 34178637, 2021). "Angiopoietin-2 (Ang2) also functions as a pro-angiogenic factor, predominantly expressed by tumor endothelial cells." (PMID 33804039, 2021). "In this study, we aimed to validate the group of reported candidate-CCA biomarkers, namely S100A9, MUC5AC, TGF-β1, angiopoietin-2, and the commonly used tumor marker, CA19-9, in the sera of CCA patients compared with healthy people and other GI cancer groups." (PMID 33806004, 2021). "Bgn KO also impaired tumor angiogenesis and normalized tumor vasculature by repressing tumor necrosis factor-ɑ/angiopoietin 2 signaling." (PMID 33966638, 2021). "Studies on angiogenesis have emphasized the importance of others angiogenic factors involved in tumor growth such as angiopoietins, in particular angiopoietin 1 (Ang1) and angiopoietin 2 (Ang2), currently proposed as biomarkers of GB." (PMID 34298658, 2021). "Angiopoietin-2 can be secreted by tumor ECs, which leads to an autocrine activation of STAT3 signaling with secretion of CCL2 and higher expression of ICAM1." (PMID 34073394, 2021). "The GS value of ANGPT2 to tumor grade was 0.909, P= 0.006 (SERPINE1, P= 0.025; HS3ST2, P= 0.103; COL1A1, P= 0.040; COL5A2, P= 0.006)." (PMID 33758610, 2021). "Angiopoietin-2 is mainly secreted by endothelial cells at sites of active vascular remodeling, and is involved in tumor initiation." (PMID 34167524, 2021). "Recent studies indicated that exosomal ANGPT2 secreted by HCC cells can induce tumor angiogenesis via a novel pathway that is different from the classic ANGPT2/Tie2 pathway, and blocking ANGPT2 is a promising therapeutic strategy for HCC." (PMID 34049287, 2021). "Tumor-derived angiopoietin-2 (Ang-2) induces chemotactic activity in TEMs, which have been associated with resistance to therapies that block VEGF and VEGFR-2 and with the development of an invasive phenotype." (PMID 34771577, 2021). "Lastly, angiopoietin-2 (Ang2), which is stored in Weibel Palade bodies of ECs, is a highly interesting angiocrine factor controlling tumor progression." (PMID 34073394, 2021). "Targeting ANGPT2 signaling in tumor vasculature can restore vascular stability and decrease tumor growth and metastasis." (PMID 33966638, 2021).